LEP (leptin)
Diseases named in the same sentence as LEP in open-access papers (continued):
Sharing a sentence is not in itself a finding about the gene and the disease.
Insulin resistance (continued). "PTPN1 found from the network study is linked to the common network pathway and modulates insulin resistance through Jak-Stat, insulin receptor substrates (IRS1 and IRS2) and leptin signaling pathway." (PMID 30674322, 2019). "Obese dogs express alterations in cardiac function, insulin resistance, dyslipidaemia, hypo-adiponectinaemia and increased concentrations of inflammatory markers and leptin." (PMID 31091785, 2019). "A recent report also indicated that isothiocyanate-rich Moringa oleifera extract reduced weight gain, insulin resistance, and hepatic gluconeogenesis in mice by reducing plasma insulin, leptin and resistin." (PMID 31220177, 2019). "And plasma omentin-1 levels were inversely correlated with body mass index (BMI), waist circumference, leptin levels, and insulin resistance, and positively correlated with adiponectin and high-density lipoprotein (HDL) levels." (PMID 31736870, 2019). "At the beginning and after eight weeks of follow-up, body composition was evaluated by using dual-energy X-ray absorptiometry and lipid profile, insulin resistance, C-reactive protein, adiponectin, leptin and nesfastin plasma concentrations were analyzed." (PMID 31480676, 2019). "We proposed the adiponectin/leptin (Adpn/Lep) ratio as a marker of adipose tissue dysfunction and inflammation, being better correlated with insulin resistance than adiponectin or leptin alone." (PMID 31484347, 2019). "Sex-based differences in the quantitative genetic structure of disease traits is common, including insulin resistance in mouse models, leptin resistance and the biochemical operation of leptin." (PMID 31661517, 2019). "Fasting serum leptin, another marker of insulin resistance, was lower in the MCT-LC diet groups than the control group, but the differences were not significant." (PMID 31744125, 2019). "As it is known, adiponectin enhances insulin sensitivity, resistin increases insulin resistance, and leptin has anorexigenic activity." (PMID 30996303, 2019). "In previous studies on saffron, authors determined that this plant reduces appetite, decreases insulin resistance, and reduces serum leptin levels." (PMID 32133067, 2019). "At baseline, ATX levels were positively associated with BMI, fat mass, insulin, insulin resistance (HOMA‐IR), and leptin and negatively with fat‐free mass." (PMID 30821134, 2019). "Leptin treatment can also improve insulin resistance, and glucose and lipid imbalances in some type 2 diabetic models." (PMID 31718027, 2019). "In conclusion, IF significantly improves glycemic control and insulin resistance with a reduction in BMI, a decrease in leptin level, and an increase in adiponectin concentration in the general population without chronic metabolic disease." (PMID 31601019, 2019). "In severely obese female patients, the abnormal adipogenesis is related to insulin resistance and leptin/adiponectin ratio." (PMID 31189474, 2019). "Testosterone is able to decrease leptin levels and also provides a mechanistic explanation for alterations in insulin resistance via changes in testosterone/leptin signaling." (PMID 31849810, 2019). "In boys, SSB intake corresponded with higher C-peptide insulin resistance (Q2 vs. Q1: 0.06 [−0.06, 0.19], Q3 vs. Q1: 0.01 [−0.12, 0.14], Q4 vs. Q1: 0.17 [0.04, 0.30] ng/mL; P-trend = 0.03) and leptin (P-trend = 0.02)." (PMID 31108933, 2019). "The content in exosomes derived from adipose tissue—e.g., leptin and adiponectin—links readily insulin resistance to the secretion of exosomes." (PMID 31828161, 2019). "Fish proteins have high levels of taurine, which is reported to help ameliorate hyperglycemia and dyslipidemia by reducing insulin resistance and leptin levels." (PMID 31382619, 2019). "Resveratrol supplementation in obese men for 1 month reduced glucose, insulin resistance index and leptin level and lowered inflammatory markers (e.g., TNF-α, leukocytes)." (PMID 30931309, 2019).
Insulin resistance (continued). "The main clinical features of this participant were leptin levels higher than expected for the BMI, and the presence of insulin resistance observed as hyperinsulinemia, increased HOMA-IR (4.23), and Acanthosis Nigricans." (PMID 31035493, 2019). "Previous studies focus on the acute action of leptin on synaptic plasticity, whereas recent studies report insulin resistance afflicts circulating leptin levels and affects central neuroplasticity and cognitive functions." (PMID 31718027, 2019). "We have previously reported that the risk of type 2 diabetes, early impaired glucose tolerance, and insulin resistance can be predicted using fasting levels of adiponectin, leptin, and insulin." (PMID 31379415, 2019). "After 10 weeks, mice that continued on the high-fat diet showed significant increases in body weight, blood glucose, insulin, and leptin levels and exhibited impaired oral glucose tolerance, insulin resistance, and pancreatic β-cell dysfunction." (PMID 31382619, 2019). "In contrast, resistin, another adipocyte-secreted hormone, induces insulin resistance and hypothalamic leptin insensitivity and strongly increases circulating leptin concentrations in transgenic mice with moderate adipocyte-specific resistin overexpression." (PMID 31514318, 2019). "The agouti-mice (Ay/a) have the increased expression of ASIP1, which antagonizes MC4R and provokes weight gain, fat deposition, glucose intolerance, the leptin and insulin resistance, and the impaired transport of leptin into the brain structures." (PMID 30870482, 2019). "In a series of rat models, decreased visceral fat mass, obtained either by caloric restriction or surgical resection, improved age-related insulin resistance, possibly via alteration of leptin and other adipokine secretions." (PMID 30923512, 2019). "In obese patients, excessive accumulation of adipose tissue leads to elevated levels of circulating free fatty acids and increased expression of serum adipokines, such as leptin, visfatin, and cytokines, which ultimately leads to insulin resistance." (PMID 31440472, 2019). "In fact, high-plasma leptin concentrations have been correlated to insulin resistance in humans and in insulin-resistant dogs." (PMID 31091785, 2019). "It seems, therefore, that the lowering of adiponectin, leptin and resistin concentrations obtained following liposuction and the reduction of insulin resistance markers can be assessed as its positively modulating effects on fat metabolism." (PMID 31500356, 2019). "Leptin, adiponectin, glycoalbumin, and body mass index also were correlated well with plasma glucose levels and insulin resistance index." (PMID 31379415, 2019). "The morbidly obese groups presented significantly higher levels of insulin, free fatty acids (FFA), triglycerides, leptin, adiponectin, and homeostasis model assessment of insulin resistance (HOMA-IR) results (p < 0.05)." (PMID 30813326, 2019). "Obesity adds to the genetic susceptibility, insulin resistance due to FFA and tumor necrosis factor -α (TNF-α), an inhibitor of insulin receptor kinase activity, leptin-regulating hormone appetite and adiponectin." (PMID 30931309, 2019). "Leptin and adiponectin independently and inversely influence such phenomena as the insulin resistance of tissues, glucose metabolism, and vessel inflammation." (PMID 31252598, 2019). "Adolescents with high body fat presented higher values of anthropometric measurements (WC, NC, and WtHR), gynoid and android BF%, and higher concentrations of insulin, insulin resistance (IR), and leptin." (PMID 31933541, 2019). "Our findings clearly demonstrated that HbA1c as well as leptin, adiponectin, and insulin were strongly related to both glucose tolerance and insulin resistance." (PMID 31379415, 2019).
Insulin resistance (continued). "At present, the possible mechanisms are as follows: obese patients are often accompanied by insulin resistance (hyperinsulinemia), abnormal fat metabolism (leptin, adiponectin disorders), hyperglycemia, hyperlipidemia, and chronic inflammation." (PMID 31440472, 2019). "Probiotic supplementation (group 3) reduced weight gain, and there were positive effects on the levels of fasting plasma glucose, insulin, homeostatic model assessment-insulin resistance, triglycerides, inflammatory markers, leptin, and chemerin." (PMID 31284705, 2019). "Leptin is an adipose tissue hormone that modulates appetite and insulin activity in target cells, inducing insulin resistance." (PMID 31191339, 2019). "Despite the introduction of several mechanisms, the precise mechanisms of olanzapine induced weight gain have not yet been determined, but in addition to increased appetite; insulin resistance, and increased serum leptin, are proposed." (PMID 32133067, 2019). "The involvement in insulin resistance of the high leptin and low adiponectin levels benefits from extensive experimental research; adiponectin reduces hepatic glucose output and stimulates glucose utilization in muscles." (PMID 30457109, 2019). "Animals and human models showed that inhibition of leptin action results in food assumption and insulin resistance." (PMID 31824900, 2019). "It has metabolic adverse effects such as weight gain, increase in adipose tissue mass, blood leptin, insulin levels, insulin resistance, type 2 diabetes, high blood pressure and disruption of fat profile." (PMID 32133067, 2019). "The study revealed three distinct biologically meaningful subgroups one with higher insulin resistance and the other with higher leptin levels." (PMID 31024923, 2019). "Aging is accompanied by elevated visceral adiposity, serum leptin, and insulin resistance, as well as decreased sensitivity to leptin." (PMID 31788330, 2019). "Specifically, improved metabolic parameters, including fasting glucose, insulin resistance, serum leptin, urinary catecholamines, and liver triglycerides, were observed." (PMID 30818779, 2019). "The increase of fat mass leads to higher leptin levels, inducing a proinflammatory response and insulin resistance." (PMID 30764545, 2019). "Previous studies showed that leptin secreted from adipocyte tissue is related to the development of insulin resistance and diabetes." (PMID 31052312, 2019). "Maternal whole blood glucose, serum leptin and insulin concentrations, and homeostatic model assessment of insulin resistance (HOMA-IR) were all higher in high-fat fed dams compared to controls." (PMID 31772245, 2019). "In patients with skin tags, serum leptin is significantly upregulated and positive correlations are also found between serum leptin and insulin resistance calculated by homeostasis model assessment (HOMA-IR)." (PMID 31824416, 2019). "Multiple studies have demonstrated the effectiveness of exogenous leptin administration on improving insulin resistance in different obese and diabetic rodent models." (PMID 31718027, 2019). "On the other hand, it is not possible to exclude the possibility that HPH affected energy metabolism and weight gain resulting in the improvement of leptin and insulin resistance." (PMID 31382619, 2019). "Changes in BMI and waist circumference correlated inversely with changes in ghrelin concentrations, and positively with changes in leptin concentrations, the latter also being correlated with changes in insulin resistance." (PMID 29599686, 2018). "In fact, similar to the manifestation of insulin resistance, the majority of obese patients and diet-induced obese mice show leptin resistance." (PMID 29498693, 2018). "Although insulin resistance represented by the HOMA index was associated with anthropometric variables and with serum leptin, adiponectin, chemerin, and IL-6 concentrations, in our study, no statistically significant relations with PTC staging were identified." (PMID 30627158, 2018).
Insulin resistance (continued). "It has been proposed that a useful index of metabolic diseases is the ratio of leptin to adiponectin (L/A), which shows a better correlation to insulin resistance than the level of leptin and adiponectin alone." (PMID 29472867, 2018). "Genetic deletion of Ire1α in pro-opiomelanocortin (POMC) neurons induced ER stress, as well as leptin and insulin resistance in these cells." (PMID 29921793, 2018). "A wealth of clinical studies suggests that OSA can exacerbate T2D, and animal studies have echoed this conclusion demonstrating that rodents exposed to IH show impairments in glycemic control, insulin resistance, and altered leptin levels." (PMID 30127766, 2018). "In the present study, insulin resistance and increased levels of serum leptin, both of which are involved in the recurrence of HCC, were observed in the patients with higher VFMI." (PMID 29581826, 2018). "All of which can also produce an increased risk of insulin resistance, a high circulating level of LDL, elevated triglycerides, increased risk of developing obesity, and rising resistance to leptin." (PMID 30154843, 2018). "Chronic leptin replacement therapy has been shown to reverse liver and muscle insulin resistance and fasting hyperglycaemia in patients displaying a severe lipodystrophy." (PMID 29534036, 2018). "The N-BMI-HF girls had increased abdominal and hepatic fat content and increased insulin resistance, plasma leptin and Hs-CRP concentrations (p < 0.05) as compared to their N-BMI-NF counterparts." (PMID 29914129, 2018). "Taken together, these data suggested that by inducing a decrease of adiponectin and leptin expression, BaP and PCBs are also potent to promote the development of insulin resistance states." (PMID 29534036, 2018). "In the present study serum adiponectin and leptin have been measured and their relationships with gender, age, BMI, waist circumference, fasting insulin, and insulin resistance have been considered in a West African population." (PMID 29890036, 2018). "The L/A ratio has been proposed as a better index of metabolic diseases, than independent levels of leptin and adiponectin, since it shows a better correlation to insulin resistance." (PMID 30034345, 2018). "Recombinant leptin has been successfully used in the treatment of insulin resistance and hepatic steatosis in patients with lipodystrophy and NASH." (PMID 29910742, 2018). "Remarkably, leptin uptake in several brain regions was increased upon administration of triglycerides while at the same time leptin- and insulin resistance were observed." (PMID 29849009, 2018). "In type 2 diabetic rats, the treatment with ASE reduced blood glucose, insulin resistance, leptin and IL-6 levels, lipid profile, and vascular dysfunction." (PMID 29920546, 2018). "PPARG is involved in lipid and glucose homeostasis, decreased plasma leptin level, and insulin resistance." (PMID 29495392, 2018). "GEB can reduce insulin resistance by reducing fat accumulation in adipocytes, and activating fat oxidation and enhancing leptin signaling in obese rats." (PMID 30524286, 2018). "Multiple lines of evidence showed the influence of leptin in the metabolism of glucose and pathogenesis of insulin resistance and diabetes." (PMID 30584543, 2018). "In the present study, implications of BCAA elevations in relation to maternal ppBMI and maternal metabolic impairment were supported by other serologic markers of insulin resistance including an elevated leptin/adiponectin ratio." (PMID 30208589, 2018). "Leptin and insulin show a strong relationship, and leptin resistance is accompanied by hyperinsulinemia and insulin resistance." (PMID 29599686, 2018). "Adiponectin is the most important factor for increasing insulin sensitivity, while factors including leptin, resistin and C-reactive protein are known to be correlated with the increase of insulin resistance." (PMID 29793496, 2018).
Insulin resistance (continued). "Leptin is known to induce insulin resistance, hepatic steatosis and has proinflammatory role and also contributes to fibrosis, whereas, adiponectin has anti-inflammatory and insulin sensitizing effect." (PMID 30026586, 2018). "Together, this suggests that altering leptin signaling in POMC neurons results in rapid-onset hepatic insulin resistance." (PMID 29528284, 2018). "Other factors including PTP1B and especially TNF-α, slowly return toward normal values, which would contribute to maintain leptin and insulin resistance at the early stages." (PMID 29367725, 2018). "A significant positive correlation was observed between leptin and 30/15 coefficient (r = 0.396; p = 0.036) after adjusting for insulin resistance and triglycerides." (PMID 29329523, 2018). "Plasma concentrations of adiponectin and leptin, as well as homeostatic model assessment of insulin resistance were also evaluated." (PMID 30279628, 2018). "Leptin treatment prior to IH reduces insulin resistance and hyperlipidemia and improves endothelial relaxation and vascular stiffness in ob/ob mice." (PMID 30127766, 2018). "Although pioglitazone improved insulin resistance and hypothalamic leptin action in HFD-fed mice, it increased food intake via activation of the hypothalamic adiponectin receptor 1/AMP-activated protein kinase pathway." (PMID 29979770, 2018). "HFD-fed offspring of HFD-fed mothers had increased body weight, fat mass, and glucose intolerance with increased insulin, leptin, insulin resistance, and hyperphagia compared with offspring of chow-fed mothers." (PMID 29483369, 2018). "Insulin resistance was correlated with fasting levels of insulin and leptin/adiponectin (r = 0.913); of insulin, retinol binding protein 4 and leptin/adiponectin (r = 0.903); and of insulin, glycated albumin, and leptin/adiponectin (r = 0.913)." (PMID 29610560, 2018). "A study by Cnop established the relationship between intra-abdominal fat, insulin resistance, and leptin." (PMID 30405010, 2018). "Numerous studies report that serum concentrations of FGF-21 are elevated in obese individuals and positively correlate with insulin resistance, BMI, % fat mass and circulatory concentrations of leptin and LDL." (PMID 29760587, 2018). "These girls present increased fat mass, abdominal fat deposits, insulin resistance and increased plasma concentrations of insulin and leptin." (PMID 29914129, 2018). "This is in agreement with the marked reduction in the circulating levels of NEFA, resistin and leptin observed in RNAi treated rats, whose high levels were positively correlated with adiposity, insulin resistance, diabetes and metabolic syndrome." (PMID 29500410, 2018). "Leptin and adiponectin have opposing effects on low-grade adipose tissue inflammation and insulin resistance, with leptin upregulating proinflammatory cytokines, and adiponectin having the opposite effect." (PMID 29543710, 2018). "Proinflammatory cytokines and high levels of leptin, secreted from the adipose tissue, also contribute to the induction of insulin resistance in T2DM." (PMID 29920546, 2018). "Fasting plasma glucose, insulin, leptin, lipids and homeostasis model assessment of insulin resistance values were measured, and an oral glucose tolerance test was performed." (PMID 30275911, 2018). "In N-BMI girls, insulin resistance, plasma insulin and leptin correlated with BMI and body fat % (p < 0.05)." (PMID 29914129, 2018). "Stimulation of the rat L6 skeletal muscle cell line with recombinant leptin reduced phosphorylation of the insulin receptor substrate-1 (IRS-1) and impaired glucose uptake, suggesting that leptin promotes insulin resistance." (PMID 29760587, 2018). "In general, the plasma leptin: adiponectin ratio is a useful measure of insulin resistance and predictor the presence of metabolic syndrome." (PMID 30360437, 2018).